BRCA2 (BRCA2 DNA repair associated)
Diseases named in the same sentence as BRCA2 in open-access papers (continued):
Sharing a sentence is not in itself a finding about the gene and the disease.
tumor (continued). "Given that inheritance of a BRCA1 or BRCA2 mutation correlates with earlier onset of disease, aggressive tumor behavior, and heightened recurrence risk, targeted therapies such as oral poly(ADP-ribose) polymerase (PARP) inhibitors offer potential additional treatments for these patients." (PMID 38826792, 2024). "Gene panel testing allows for the analysis of multiple genes beyond BRCA1 and BRCA2 that may also be associated with tumour development and/or treatment response, and their feasibility for guiding BC treatment is being considered in clinical trials." (PMID 39215191, 2024). "Our case study revealed that the pathogenic BRCA2 c.5946del germline variant can be associated with an unusual tumour spectrum, which may lead to a delayed diagnosis of a hereditary tumour predisposition." (PMID 39702187, 2024). "Interestingly, patients with a low TMB but BRCA2 mutation had the same OS as patients with highly mutated tumours did, suggesting neoantigen-independent mechanisms of immunogenicity." (PMID 39271762, 2024). "Ser3291 is located at the C-terminus of BRCA2, and the loss of phosphorylation of Ser3291 may eliminate the tumor suppressor function of BRCA2." (PMID 38184581, 2024). "However, when we assessed the associations between BRCA2 mutation status and tumor features, chemotherapy regimens and clinical outcomes in PanC patients as well as with the overall and progression-free survival." (PMID 36717774, 2023). "Patients with BRCA1- and BRCA2-mutated tumors treated with PARPis often have dramatic treatment responses as the synthetic lethality induced by the PARPi leads to cell death within the tumor." (PMID 36968138, 2023). "The identified substructure among the mutationally quiescent non-BRCA1/BRCA2 tumours may point to common aetiological mechanisms within the subgroups." (PMID 37316882, 2023). "Additionally, some DGC patients tested negative for CDH1/CTNNA1 gene but had pathogenic variants in related tumor susceptibility genes, such as BRCA2, ATM, SDHB, PRSS1, MSR1, STK11, and PALB2." (PMID 37393258, 2023). "Germline BRCA2 mutations have especially been associated with a poor prognosis and have been found to be an independent prognostic factor for PCa patients, and this applies even in cases with a limited tumor volume and low histopathological grade." (PMID 37511177, 2023). "While most PDAC cases are driven by canonical gain-of-function KRAS mutations, ConDoR reveals that the tumor analyzed here is driven by a truncal BRCA2 stop-gained mutation (p.Y600*), which likely inactivated the BRCA2 protein, a tumor suppressor essential for homologous recombination repair." (PMID 38037115, 2023). "Interestingly, its morphology is more epithelial and its growth rate slower than PEO1, suggesting an epithelial-like subpopulation acquired a novel BRCA2 mutation that allowed it to outcompete a faster-growing but drug-responsive majority of tumor cells." (PMID 37568736, 2023). "Interestingly, these data demonstrated that CRISPR KO of FBXO9 led to a CERES project score of ~−0.2; this trend is similar to BRCA1 and BRCA2, which are well-known tumor suppressors associated with DNA damage repair." (PMID 38136595, 2023). "This agrees with what was identified for BRCA2-deficient tumours in prior studies." (PMID 36883553, 2023). "Only one primary–recurrent tumor pair (P1-R1) exhibited BRCA2 mutations." (PMID 37761830, 2023). "BRCA1 and BRCA2 are tumor suppressor genes that encode proteins, which are responsible for repairing disruptions in damaged DNA that could otherwise result in tumor formation." (PMID 37185387, 2023). "Notably, defects in the homologous recombination repair (HRR) pathway, regulated by BRCA1 and BRCA2 proteins, are linked to multiple tumor types, including breast, ovarian, and gastric cancers." (PMID 37958290, 2023).
tumor (continued). "In fact, in preclinical models, mutations in Brca1 and Brca2 have been shown to influence response to immune checkpoint inhibitors (ICIs), with anti-PD-l blockade only improving survival of mice harbouring Brca1-null tumours." (PMID 38017453, 2023). "However, the olaparib monotherapy did significantly improve the survival of mice harbouring Brca2-deficient tumours (68 vs. 52 days)." (PMID 38017453, 2023). "Mucinous tumours provided supporting evidence against BRCA2 variant pathogenicity in individuals diagnosed both before the age of 50 (LR: 0.36 (95% CI: 0.16–0.80), supporting evidence) and after the age of 50 (LR: 0.42 (95% CI: 0.21–0.87), supporting evidence)." (PMID 37076566, 2023). "A frontal sinus‐based neoplasm had a loss of function BRCA2 K3326* variant." (PMID 36125633, 2023). "We hypothesize that the isoform switch may represent a mechanism by which BRCA1 mutation-associated tumors can modulate BRCA2 transcript stability to retain HR function and enhance tumor survival." (PMID 36344544, 2022). "Alternatively, the suppression of SSA by hRad52 S346X may block tumour formation in BRCA2-deficient cells, given the loss of two mechanisms of DSB repair." (PMID 36010882, 2022). "One of the mechanisms that makes tumor cells HRR-proficient is BRCA2-reversion mutation." (PMID 36012138, 2022). "Importantly, the authors noted a GC with a somatic BRCA2 mutation that presented a HR deficient tumor mutation signature." (PMID 36497436, 2022). "It should be noted that similar but different phenotypes of SBS3 may arise dependent on the underlying cause and even tumor type, e.g., BRCA2 and PALB2 inactivation lead to larger deletions when compared to BRCA1- and RAD51-related HRD." (PMID 36077694, 2022). "The number of tumours with a BRCA2 mutation in the dataset was too low for a similar analysis." (PMID 35501389, 2022). "As expected, mutations in the AR and DNA repair genes included in our panel were the most common ones, in particular, the ATM and BRCA1/BRCA2 genes, and they seemed to drive high tumor mutation load and rapid polymetastatic spread after the first oligorecurrence treated with SBRT." (PMID 35740343, 2022). "Interestingly, BRCA1 and BRCA2 were shown to cause distinct changes in the tumor immune microenvironment, with BRCA2-mutated tumors having higher gene expression of both adaptive immunity– and innate immunity–related pathways." (PMID 35703181, 2022). "Our in vitro results demonstrated that the DNA damage inflicted by pyridostatin in BRCA2‐deficient cells is repaired after removal of the drug, suggesting that the toxicity of this compound is reversible and tumour growth may recover in the long term." (PMID 35107878, 2022). "We hypothesize the response of the patient's tumor to rucaparib was likely driven by DNA damage repair deficiency caused by homozygous loss of all BRCA2 exons." (PMID 35978838, 2022). "Mutation of BRCA2 was shown to promote tumor sensitivity towards PARP inhibitors." (PMID 35899106, 2022). "In addition, the heatmap for patient P1 shows strong signal that FOXP1 mutates on the trunk of the tumor tree, while BRCA2 has a high probability of having mutated on the trunk of the tree for patient P2." (PMID 36459515, 2022). "A three‐drug combination consisting of pyridostatin, NU‐7441 and paclitaxel can effectively suppress growth or even eradicate BRCA1‐ or BRCA2‐deficient tumours and we propose that this triple combination represents an effective therapeutic strategy against BRCA‐mutated cancers." (PMID 35107878, 2022). "As Rad52 is required for cellular proliferation in BRCA2-defective cells, silencing of Rad52 could cause BRCA2-defective tumour cells." (PMID 36010882, 2022). "Homologous recombination-deficient HRD-Dup (BRCA1 mutant-like) and HRD-Del (BRCA2 mutant-like) tumours harboured inflammatory signalling and ongoing immunoediting, reflected in loss of HLA diversity and tumour infiltration with highly differentiated dysfunctional CD8+ T cells." (PMID 36517593, 2022).
tumor (continued). "On the other hand, C‐NHEJ repair may enable BRCA2‐deficient and tumours to develop resistance to pyridostatin, in the long term." (PMID 35107878, 2022). "Overall, this evidence indicates that BRCA2, forming complexes with specific proteins, may control transcription of genes implicated in tumor development and/or progression." (PMID 35734584, 2022). "A part of this effect may be related to the higher tumour primary chemosensitivity related to BRCA2 mutation, as suggested here with KELIM." (PMID 35361918, 2022). "The observation that lymph node involvement is more frequent in BRCA2 mutation carriers may be the result of tumor biology." (PMID 35507134, 2022). "Interestingly, ARID1B1 and BRCA2 mutations were found to be SVZM+ tumor exclusive by deep NGS of the Heidelberg cohort as well as EPHA1, DECAF12L2, and ADCY5 by WES in the TCGA cohort." (PMID 35660939, 2022). "Only one patient (in sotiga/nivo/chemo) had a pathogenic tumor variant of BRCA2." (PMID 35662283, 2022). "Tumor mutation burden was significantly higher in the BRCA2-altered samples." (PMID 36362213, 2022). "Tumours with BRCA1 or BRCA2 mutations are highly sensitive to PARP inhibitors." (PMID 36010882, 2022). "As BRCA2 depletion results into R-loop accumulation, the observation may explain the enhanced G4 binders activity in BRCA2-deficient tumours." (PMID 36114513, 2022). "Based on these findings, it could be speculated that through upregulation of C19orf57 and subsequent sequestration of BRCA2, tumours promote genome instability and loss of strict control over the cell cycle." (PMID 35987928, 2022). "If the repair of DNA is inhibited, it will induce apoptosis to clear the cells that may be mutated; however, once BRCA1/BRCA2 is mutated, DNA repair cannot be completed, and the progression of tumor development is promoted." (PMID 34198652, 2021). "Although most BRCA1/2 carriers developed later-onset esophagogastric cancer, 28.6% of patients had early-onset disease, including a 35-year-old BRCA2 carrier whose tumor also carried a second somatic BRCA2 variant, suggesting that the germline BRCA2 variant contributed to carcinogenesis." (PMID 34251444, 2021). "Gene expression variability in BRCA2-associated tumours was inconsistent, with the Waddell dataset showing comparable variability with BRCAx tumours, but the Larsen dataset showing only a modest 11.1% (95% CI 10.6–11.6) increase in variability in BRCA2-associated tumours compared to BRCAx tumours." (PMID 34287743, 2021). "Interestingly, patient-derived tumor xenografts obtained from three patients with BRCA2 germline mutations showed a higher rate of IDC-P components than samples derived from sporadic cases." (PMID 34884926, 2021). "Mutually exclusive CTG expression with inactivating mutations in the major HR genes, BRCA1 and BRCA2, that drive tumor formation may indicate functional significance." (PMID 34481156, 2021). "In contrast, somatically mutated BRCA2 variants identified by sequencing of tumor DNA may correlate well with functional assays designed to measure chemotherapeutic response." (PMID 34065235, 2021). "BRCA2 mutation has a known core function in homologous recombination (HR), one of the most commonly altered DNA damage pathways in cancer, which results in a higher tumor mutational load." (PMID 34195090, 2021). "Tumor samples with defective BRCA2 display the defined HR-defective mutational signature 3 with single-base substitutions (SBSs), ID6 with small insertions and deletions, and structural variants with non-clustered deletions < 100 kb and reciprocal translocations." (PMID 34440403, 2021). "In tumor fragments, the BRCA2 and USH2A genes showed many variants in both species." (PMID 34680380, 2021). "Notably, knockdown of DDX11 in PEO1 and Capan-1 sensitive (S) as well as resistant (R) clones rendered the BRCA2-mutated tumor cells sensitive to olaparib." (PMID 33879618, 2021).
tumor (continued). "Germline testing is also recommended for patients with pathogenic/likely pathogenic BRCA2 mutations identified through tumor sequencing and should also be considered in patients with alterations in other genes linked to cancer predisposition syndromes (i.e., BRCA1, ATM, MMR genes)." (PMID 33625671, 2021). "It is possible that there are inherent differences in response to PARPis based on whether tumours have a BRCA1 or BRCA2 mutation." (PMID 34445211, 2021). "Importantly, we find that upregulated p21 expression is essential for the survival of BRCA2-deficient cells and tumours." (PMID 34389725, 2021). "Mutations in BRCA2 are associated with an increased risk for a variety of tumor types." (PMID 34356050, 2021). "In turn, the study of separation of function variants of BRCA2, and of other tumor suppressors, identified in patients may provide insights on the specific function(s) that drive tumorigenesis when defective." (PMID 34359619, 2021). "In addition, BRAF p.V600E, p.G466V, and p.L597R, as well as BRCA2 mutations, were also considered actionable based on the observations from other tumor types." (PMID 34594355, 2021). "In addition, in up to 8% of affected patients, somatic BRCA1 and BRCA2 mutations can be found in tumor specimens." (PMID 34202525, 2021). "Also, in support of this is the high proportion of ER-positive tumours among young BRCA2 mutation carriers." (PMID 32939053, 2020). "However, there are a few examples of interest for performing immunohistochemistry to evaluate BRCA1 protein and nuclear expression for BRCA2-associated tumor." (PMID 32481735, 2020). "Additionally, BRCA1 (3326A>T) and BRCA2 (1342A>C) mutations were also detected in tumor tissues of II3." (PMID 32356124, 2020). "Additionally, the presence of a large, independent cohort of BRCA1/2 mutation carriers in the validation cohort provides strong evidence to support the increased prevalence of MF/MC tumours in BRCA2 mutation carriers." (PMID 32022473, 2020). "This suggests that the location of the mutation in the BRCA2 gene might relate to how the tumour responds to ovarian hormones." (PMID 32939053, 2020). "Interestingly, one tumor with a germline BRCA2 variant also harbored a low allele frequency of somatic BRCA2 mutation in addition to LOH, suggesting clonal heterogeneity in the tumor over time, with independent events leading to biallelic inactivation." (PMID 33067557, 2020). "Many laboratories are now performing BRCA1/BRCA2 testing in formalin-fixed paraffin-embedded (FFPE) tumor samples to detect germline and somatic variants to identify, in a single test, those patients with somatic and germline variants who are most likely to benefit from PARPi therapy." (PMID 33008098, 2020). "Acquiring a somatic BRCA2 mutation in a single primary tumour could result in a differential response to targeted therapies that would not be predicted based on the typical single site sampling performed in clinical practice." (PMID 32392735, 2020). "The loss of heterozygosity and acquisition of a secondary mutation restoring the open reading frame suggest that this somatic BRCA2 mutation (c.5446_5449delCTAG) was the driver for tumour formation (i.e. is a pathogenic mutation) and the cause of the initial platinum sensitivity." (PMID 31577852, 2020). "Under the assumption that BRCA1/BRCA2 germline variants induce recognizable effects on tumor transcription, we assessed whether tumors from BRCA1/BRCA2 carriers have homogeneous gene-expression profiles." (PMID 32997669, 2020).
tumor (continued). "Hence, together with BRCA1, BRCA2 acts as a tumor suppressor; mutations in these genes will impede the cell’s ability to repair DNA damage, especially DNA DSBs." (PMID 32005245, 2020). "Because of this phenomenon, HBOC patients with germline BRCA1 and BRCA2 mutations have an increased risk for the development of a number of neoplasms, particularly those arising in the breast as well as ovary and fallopian tube (hereby referred to as “tubo-ovarian cancer”)." (PMID 33117676, 2020). "Signature 3 was more common among basal-like tumours, and is associated with mutations in the BRCA1 and BRCA2 genes and defective double-strand break repair by homologous recombination, suggesting a link between this erroneous repair mechanism and basal-like tumour development." (PMID 32164620, 2020). "Alternatively, the suppression of SSA by hRAD52 S346X may block tumor formation in BRCA2‐deficient cells because of their loss of two mechanisms of DSB repair, leading to the increased persistence of DSBs and apoptosis." (PMID 32175645, 2020). "In addition, only 9 and 3 genes were differentially expressed between sporadic tumours and BRCA1- and BRCA2-associated tumours, respectively." (PMID 33081408, 2020). "Altogether, our results show that BRCA2 mutations sensitize tumor cells to olaparib, and that combination of IR with olaparib may also constitute an option for BRCA2 proficient tumors." (PMID 32630796, 2020). "Thus, chlorambucil is active against BRCA2‐deficient tumours even at doses lower than the equivalent doses used in the clinic." (PMID 31273933, 2019). "Then, the results that ARID1A and BRCA2 were more frequently mutated in diffuse-type C-II GCs than in C-I GCs suggest that many mutations may be induced in the tumor by the loss of function of these tumor suppressors." (PMID 30866995, 2019). "As in the case of tumours deficient in BRCA1/BRCA2, the deficient DNA repair in RECQL-deficient tumours could increase their sensitivity to other drugs blocking compensatory DNA repair mechanisms." (PMID 30610487, 2019). "Finally, we provide evidence to support a link between BRCA2 mutation, tumor diploidy, and poor survival outcome." (PMID 30930946, 2019). "However, the frequencies of these mutations were low in the tumor tissues (0.2% for BRCA2 and 3.1% for STAG2), suggesting subclonal events." (PMID 32914024, 2019). "Several trials with immune checkpoint inhibitors as a single agent treatment or as combination therapy are currently ongoing in both unselected as in immunogenic subtypes, such as those harboring microsatellite instability, high tumor mutational load or biallelic inactivation of CDK12 or BRCA2." (PMID 31727154, 2019). "Prediction of BRCA1/BRCA2 carrier status, and hence selection of women for mutation screening, may be substantially improved by combining tumor pathology with family history." (PMID 31244284, 2019). "Disrupting either the DNA annealing factor RAD52 or the A-family DNA polymerase POLQ can cause synthetic lethality with defects in BRCA1 and BRCA2, which are tumor suppressors important for homology-directed repair of DNA double-strand breaks (DSBs), and protection of stalled replication forks." (PMID 31381562, 2019). "In addition, we sequenced genomic DNA from 1 BRCA2-mutated tumor and 12 sporadic triple-negative tumors from the same study." (PMID 31182087, 2019). "Additionally, chlorambucil eradicates BRCA2‐deficient xenografts and inhibits growth of olaparib‐resistant patient‐derived tumour xenografts (PDTXs)." (PMID 31273933, 2019). "However, the intratumoral CD8 to FOXP3 ratio showed a trend to be lower in BRCA2-mutated tumors suggesting a more suppressed tumor immune microenvironment." (PMID 31549213, 2019).